CETP (cholesteryl ester transfer protein)
Description:
Involved in the transfer of neutral lipids, including cholesteryl ester and triglyceride, among lipoprotein particles. Allows the net movement of cholesteryl ester from high density lipoproteins/HDL to triglyceride-rich very low density lipoproteins/VLDL, and the equimolar transport of triglyceride from VLDL to HDL. Regulates the reverse cholesterol transport, by which excess cholesterol is removed from peripheral tissues and returned to the liver for elimination.
Synonyms: BPIFF; HDLCQ10
Tractability: Small molecule: a drug acting on it is in phase 2 or 3 trials; a structure with a bound ligand is known; a high-quality ligand is known; it has a high-quality binding pocket; it belongs to a druggable protein family. Antibody: UniProt places it where antibodies can reach, with high confidence; its Gene Ontology location is reachable by antibodies, with high confidence; UniProt predicts a signal peptide or a membrane-spanning region. PROTAC: a small molecule that binds it is known.
Target class: Ion channel; Other ion channel; Pore-forming toxins (proteins and peptides)
Chemical probes: BI-5756 (high quality)
Safety:
Unwanted effects reported when the protein is acted on. In parentheses: how it was acted on, where the effect was seen, and who reports it.
cardiovascular disease events (source: ClinPGx)
Gene: Protein-coding gene on chromosome 16 (56,961,923 to 56,983,845, forward strand). Ensembl gene ENSG00000087237.
Subcellular location: Secreted
Pathways (Reactome):
Transport of small molecules: HDL remodeling; LDL remodeling
Signal Transduction: NR1H3 & NR1H2 regulate gene expression linked to cholesterol transport and efflux
Gene Ontology:
Molecular function: cholesterol binding; cholesterol transfer activity; lipid binding; phosphatidylcholine binding; phospholipid transfer activity; triglyceride binding
Biological process: cholesterol homeostasis; cholesterol metabolic process; cholesterol transport; high-density lipoprotein particle remodeling; lipid homeostasis; lipid transport; low-density lipoprotein particle remodeling; phosphatidylcholine metabolic process; phospholipid homeostasis; positive regulation of cholesterol transport; positive regulation of phospholipid transport; regulation of cholesterol efflux; triglyceride homeostasis; triglyceride metabolic process; triglyceride transport; very-low-density lipoprotein particle remodeling; negative regulation of macrophage derived foam cell differentiation; reverse cholesterol transport; phospholipid transport
Cellular component: extracellular exosome; extracellular region; high-density lipoprotein particle; vesicle
Genetic constraint (gnomAD): Loss-of-function variants: 55 observed, 67.99 expected, observed/expected ratio (o/e) 0.81, 90% interval 0.65 to 1.01. The upper end of that interval is the gene's LOEUF score, 1.01, which puts it in group 4 of 6, group 1 being the genes least tolerant of losing a copy. Missense variants: 611 observed, 641.18 expected, observed/expected ratio (o/e) 0.95, 90% interval 0.89 to 1.02. Synonymous variants: 251 observed, 259.2 expected, observed/expected ratio (o/e) 0.97, 90% interval 0.87 to 1.08.
Homologues: Orthologues: chimpanzee CETP (98% identical), macaque CETP (96% identical), rabbit CETP (81% identical), guinea pig CETP (79% identical), tropical clawed frog cetp (50% identical), zebrafish cetp (43% identical), Caenorhabditis elegans T19C3.5 (16% identical), Caenorhabditis elegans C55C3.1 (15% identical), Caenorhabditis elegans nrf-5 (15% identical), Caenorhabditis elegans C06G1.1 (14% identical), Caenorhabditis elegans F10D11.6 (14% identical), Caenorhabditis elegans ZC513.2 (13% identical), and 2 more. Paralogues in human: LBP (20% identical), BPI (20% identical), PLTP (18% identical), BPIFC (17% identical), BPIFB4 (17% identical), BPIFB3 (14% identical), BPIFB2 (14% identical), BPIFB1 (13% identical), BPIFB6 (12% identical), BPIFA3 (7% identical), BPIFA1 (6% identical), BPIFA2 (6% identical).
Diseases named in the same sentence as CETP in open-access papers:
CETP is named in the same sentence as 166 diseases in open-access papers, as found by Europe PMC text mining. Sharing a sentence is not in itself a finding about the gene and the disease. The quoted sentences say what the papers report.
atherosclerosis (200 papers, 2006 to 2025). A disease characterized by the build-up of fatty material and calcium deposition in the arterial wall resulting in partial or complete occlusion of the arterial lumen. "The HDL-cholesterol (HDL—C) levels increased in rabbits immunized against CETP-induced neutralizing antibodies, which is linked to a reduction in the atherosclerosis process." (PMID 40823653, 2025). "CETP levels are highly genetically determined and are strongly associated with the development of atherosclerosis." (PMID 39201274, 2024). "This study utilized a DO-F1 mouse population, generated by breeding DO mice to cholesteryl ester transfer protein;ApoE3-Leiden mice to produce an F1 generation with increased susceptibility to atherosclerosis." (PMID 37944753, 2023). "The increased atherosclerosis in apoE−/− mice expressing CETP was associated with markedly increased SAA immunostaining in aortic root sections." (PMID 37004910, 2023). "Results showed that genetic deficiency of CETP protects against cholesterol diet-induced atherosclerosis in rabbits." (PMID 36361754, 2022). "The zebrafish also express cholesteryl ester transfer protein (CETP) and are susceptible to atherosclerosis, making them attractive models for studying this disorder." (PMID 35203687, 2022). "The LDL / HDL cholesterol ratio, mediated in part by CETP, is a major contributor to risk of atherosclerosis and coronary heart disease." (PMID 35703366, 2022). "In several human and animal studies, CETP facilitated the development of atherosclerosis and is a major inhibited target for reducing atherosclerosis risk." (PMID 35982498, 2022). "We claimed significance at FDR of 0.05 and identified various complex traits significant, including ischemic heart disease for the CETP variant and heart failure/atherosclerosis, hypercholesterolemia traits for GAS6 variant." (PMID 36220816, 2022). "The association between CETP and atherosclerosis was partially explained by either decreased HDL-C levels or increased plasma triglycerides." (PMID 33799675, 2021). "To shed light on the relationship between CETP and atherosclerosis, we explored the association of CETP plasma concentration and/or CETP SNPs with cIMT in a large cohort of subjects at high cardiovascular risk." (PMID 33799675, 2021). "The evidence of an inverse association between CETP and SR-B1 activity, along with a direct association between SR-B1 deficiency and increased susceptibility to atherosclerosis, supports this notion." (PMID 33799675, 2021). "A rare mutation in CETP leading to its reduced function has been linked with accelerated atherosclerosis." (PMID 32549042, 2020). "We also found widespread losses of PCSK9 and CETP genes, where loss-of-function mutations in humans protect from atherosclerosis." (PMID 33575564, 2020). "Considering higher HDL levels are associated with lower risk of atherosclerosis, the elevated level of CETP is thought to play in promoting the disease by lowering in HDL-C." (PMID 30072955, 2018). "Studying common CETP gene variants has not yet led to a consensus on the connection between CETP and atherosclerosis, and the relationship between reduced CETP function and susceptibility to atherosclerosis has proven complex and confusing." (PMID 29317793, 2017). "Here, we report a reduction in atherosclerosis in response to pharmacological stimulation of thermogenesis linked to increased HDL levels in APOE*3-Leiden.CETP mice." (PMID 28422089, 2017). "Preclinical studies supporting beneficial effects of CETP inhibitors were done in rabbits, a species that, like humans, expresses CETP and is susceptible to diet-induced atherosclerosis." (PMID 26664860, 2014). "Rabbits have higher CETP levels than humans and are highly susceptible to the induction of developing atherosclerosis and NASH." (PMID 25486007, 2014). "Mice are naturally CETP deficient and exhibit relative resistance to a high-fat diet induced atherosclerosis." (PMID 24204732, 2013).
atherosclerosis (continued). "Meanwhile transgenic exogenous CETP expression in apolipoprotein E (apoE) or LDL receptor knock-out mice exhibit an increased susceptibility to arterial atherosclerosis." (PMID 24204732, 2013). "Some animals including the mice and rats are naturally CETP deficient and according to discussed antiatherogenic role of this protein rodents are relatively resistant to atherosclerosis." (PMID 23675527, 2013). "Even though there are strong environmental factors that influence susceptibility to atherosclerosis this suggests that CETP-expressing mammals have increased risk for atherosclerosis." (PMID 23675527, 2013). "Under pathological conditions, including atherosclerosis, CETP activity is increased; moreover, in humans, CETP deficiency results in increased HDL levels." (PMID 24278703, 2012). "The role of CETP in the development of atherosclerosis became evident when it was found that CETP deficiency and the inhibition of CETP lower LDL and increase HDL levels in human plasma." (PMID 22253581, 2012). "Variation in CETP is known to affect the susceptibility to atherosclerosis and other cardiovascular diseases." (PMID 20066028, 2010). "Although there are some contrary results too, most of the studies seem to suggest that the partial inhibition of CETP appear to provide a reduction in atherosclerosis and CHD risk." (PMID 20937151, 2010). "CETP is a plasma protein that modulates atherosclerosis risk through its HDL-cholesterol reducing action." (PMID 19930639, 2009). "The present study aims to examine the influence of five single nucleotide polymorphisms (SNPs: rs1532624, rs5882, rs708272, rs7499892, and rs9989419) and their haplotypes in the CETP gene, which are strongly linked to atherosclerosis progression, on the association with AHRR." (PMID 39201274, 2024). "CETP activity is associated with increased atherosclerosis progression and/or cardiovascular risk." (PMID 35387325, 2022). "In rabbits, which have a high plasma CETP concentration and are susceptible to the development of atherosclerosis, CETP inhibition via a variety of strategies including torcetrapib, a CETP antisense oligonucleotide and an anti-CETP vaccine, reduced atherosclerosis." (PMID 36012684, 2022). "Indeed, polymorphisms in the CETP gene that affect the levels and activity of the protein alter susceptibility to atherosclerosis." (PMID 35265678, 2022). "CETP is an independent risk factor for the development of atherosclerosis." (PMID 34367144, 2021). "CETP activity is elevated in the dyslipidaemias of metabolic disease involving insulin resistance and moderate to marked hypertriglyceridaemia, and is intimately associated with premature atherosclerosis and high cardiovascular risk." (PMID 33266469, 2020). "APOE*3Leiden.CETP mice, a translational model for hyperlipidaemia and atherosclerosis, were used to evaluate the mechanisms underlying the lipid‐lowering effect of icosabutate and its effect on atherosclerosis." (PMID 32841505, 2020). "Importantly, the effects observed in the APOE*3Leiden.CETP mice confirm that icosabutate significantly inhibits the development of atherosclerosis in association with reductions in atherogenic plasma lipids." (PMID 32841505, 2020). "However, a recent study in APOE*3-Leiden.CETP mice showed that intravenous inoculation of M. bovis BCG was associated with decreased atherosclerosis formation in the aortic root after 6 weeks of infection." (PMID 33391278, 2020). "Therefore, cholesterol and cholesteryl ester transfer protein (CETP) have been considered as causative in atherosclerosis." (PMID 33122777, 2020). "CETP is expressed in humans and other animal species susceptible to atherosclerosis." (PMID 29867549, 2018). "Rare mutations leading to reduced function of CETP have been linked to accelerated atherosclerosis." (PMID 29317793, 2017).
atherosclerosis (continued). "It has been reported that a deficiency of LPL and CETP enzymes are related to the development of atherosclerosis; this deficiency could be related to mutations or variants in their genes, or by altering molecules involved in its metabolism." (PMID 26370976, 2015). "Variation in CETP levels have been correlated with lipid metabolism and insulin resistance in Type 2 diabetes, and also in association with the development of obesity and susceptibility to atherosclerosis and other CVD." (PMID 23555584, 2013). "In contrast rabbits do express CETP (like humans) and are susceptible to atherosclerosis." (PMID 23675527, 2013). "Accordingly, raising HDL induced by cholesteryl ester transfer protein (CETP) inhibition is an attractive tactic for anti-atherosclerosis, which may reduce the residual risk of cardiovascular events." (PMID 23228038, 2012). "Cholesteryl ester transfer protein (CETP) plays a major role in cholesterol metabolism, and polymorphisms within this gene may underlie the susceptibility to atherosclerosis." (PMID 23039379, 2012). "This study investigated whether the CETP gene I405V and Taq1B polymorphisms modified subclinical atherosclerosis in an asymptomatic Brazilian population sample." (PMID 23039379, 2012). "The cholesteryl ester transfer protein (CETP) has a central role in the lipid metabolism and therefore may alter the susceptibility to atherosclerosis." (PMID 21899732, 2011). "Therefore, we set out to determine the effect of inulin on the development of atherosclerosis in hypercholesterolemic APOE*3-Leiden.CETP (E3L.CETP) mice, a model that is characterized by a human-like lipoprotein metabolism and that is susceptible to the development of atherosclerosis." (PMID 30409998, 2018). "However, whether the differential effects of inulin on atherosclerosis development in APOE-deficient mice versus E3L.CETP mice are mouse model-specific and/or a result of differences in dietary composition and/or housing conditions remain to be determined." (PMID 30409998, 2018). "Further studies are warranted to further elucidate this association and to investigate whether a true biological link exits between CETP and AF or that both are associated with a common factor such as e.g. atherosclerosis, hypertension, inflammation, oxidative stress or alcohol intake." (PMID 16623947, 2006). "Consistently, CETP expression increased atherosclerosis in apoE-/- mice and enhanced SAA deposition in the aortic atherosclerotic lesions; however, there was no change in lesion development in apoE-/- mice deficient in SAA regardless of CETP expression." (PMID 40429677, 2025). "Divergent CETP activity across species further complicates the translational relevance of the findings from these models for atherosclerosis and related metabolic disorders." (PMID 41516253, 2025). "The APOE*3-Leiden.CETP model thus appears to be a relevant model for evaluating the effects of modulation of lipid metabolism on atherosclerosis development." (PMID 38428154, 2024). "Oral administration of Oxy210 formulated in WD at 4 mg/g for 16 weeks showed a significant amelioration of atherosclerosis in APOE*3-Leiden.CETP mice." (PMID 39404395, 2024). "Cholesteryl ester transfer protein (CETP) is a hepatic glycoprotein central to lipid metabolism and atherosclerosis development." (PMID 39766344, 2024).
atherosclerosis (continued). "For instance, rabbits on a high-cholesterol diet develop atherosclerosis, while rodents which lack CETP are naturally resistant to the development of atherosclerosis." (PMID 38786974, 2024). "The E3L.CETP mouse is a well-established model of human-like lipoprotein metabolism in which females develop more pronounced hypercholesterolemia and atherosclerosis than males on a Western-type diet, so we used female E3L.CETP mice in this study." (PMID 38770137, 2024). "Nevertheless, no studies have been conducted to investigate the potential association between CETP gene variants and AHRR, which are strongly associated with atherosclerosis." (PMID 39201274, 2024). "This risk factor affects numerous metabolic processes by increasing triglyceride (TG) levels, inducing cholesteryl ester-transfer-protein (CETP) to exchange cholesterol esters and TG, causing an increase in LDL levels, and contributing to atherosclerosis." (PMID 38646335, 2024). "Here, we aimed to evaluate the effect of SH42 on atherosclerosis development in APOE∗3-Leiden.CETP mice and low-density lipoproteins (LDL) receptor knockout mice, models for lipid- and inflammation-driven atherosclerosis, respectively." (PMID 38770137, 2024). "This uncertainty has motivated the exploration of alternative strategies, including CETP-targeting vaccines, to modulate CETP activity and prevent atherosclerosis." (PMID 39766344, 2024). "This study aims to compare the therapeutic potential of liver-specific Angptl3 and Angptl4 silencing to attenuate hyperlipidemia and atherosclerosis development in APOE*3-Leiden.CETP mice, a well-established humanized model for lipoprotein metabolism." (PMID 39259836, 2024). "Pre-clinical studies demonstrated delayed development of atherosclerosis in CETP knock-out studies and showed accelerated atherosclerosis in CETP knock-in models." (PMID 39150671, 2024). "A limitation of the APOE*3-Leiden.CETP mouse model is that only female mice develop atherosclerosis upon Western-type diet feeding." (PMID 38428154, 2024). "In lean hyperlipidemic E3L.CETP mice, rimonabant prevents the development of atherosclerosis, which is explained by a decrease in hepatic very low density lipoprotein (VLDL) particle formation and an increase in VLDL turnover that lowers plasma non-HDL-C." (PMID 36768835, 2023). "Mice lack CETP and thus are protected from atherosclerosis, while in transgenic mice expressing increasing levels of CETP, lower levels of HDL and higher levels of chylomicrons, VLDL and LDL were reported." (PMID 37893070, 2023). "Lesion area in aortic roots was also analyzed: atherosclerotic lesion area in the roots of apoE−/− mice was 100,405 ± 27,024 μm2, and CETP expression significantly increased atherosclerosis in apoE−/− mice (416,848 ± 80,959 μm2)." (PMID 37004910, 2023). "When early reports showed that transgenic over-expression of the CETP gene can induce atherosclerosis in mice there was an impetus to search for molecules with CETP inhibitory activity." (PMID 36897542, 2023). "In an earlier study, transgenic expression of human CETP in 2- or 4-month-old apoE−/− mice (which naturally lack CETP) resulted in a moderate ∼2-fold increase in atherosclerosis." (PMID 37004910, 2023). "Our findings are consistent with prior studies that inverting the LD cycle increased atherosclerosis in female APOE*3-Leiden.CETP and low-density lipoprotein receptor knockout mice." (PMID 37064902, 2023). "Raising HDL by CETP inhibition was ineffective in preventing atherosclerosis except by its LDL lowering effect." (PMID 36873390, 2023). "Additional GWAS hits in the shared cross-species CAD/atherosclerosis subnetworks were peripheral nodes (e.g. CETP, PLCG2, BASP1, MSR1, ST5, ASAP2)." (PMID 38060277, 2023). "In the current study, we demonstrate that TRF attenuates the development of hypercholesterolaemia and atherosclerosis in APOE∗3-Leiden.CETP mice subjected to CD." (PMID 37356205, 2023).